CXCL12 (C-X-C motif chemokine ligand 12)
Diseases named in the same sentence as CXCL12 in open-access papers (continued):
Sharing a sentence is not in itself a finding about the gene and the disease.
tumor (continued). "The down-regulated CXCL12 is linked to tumor cells to resist anoikis, survive detachment, and circulate, since CXCL12 acts as a safeguard against metastasis by inducing anoikis." (PMID 40426863, 2025). "Overall, ten studies evaluated the association between tumor expression of CXCL12 and OS in patients with GC." (PMID 40481962, 2025). "CXCL12 also recruits myeloid‐derived suppressor cells (MDSCs) and tumor‐associated neutrophils to the tumor to further create an immunosuppressive environment." (PMID 40437741, 2025). "N-acetylcysteine (NAC) modulates the tumor microenvironment by regulating the population of cancer-associated fibroblasts and inducing the activation of various cytokines, including CXCL12, SLIT2, and DCN." (PMID 40001479, 2025). "In the tumor microenvironment, tumor‐associated macrophages stimulated by CXCL12 from cancer‐associated fibroblasts upregulate the expression of PAI1." (PMID 40042093, 2025). "Tumor-associated macrophages (TAMs), recruited by CXCL12, also express HIF-1 alpha and contribute to angiogenesis and therapy resistance." (PMID 40573308, 2025). "High CXCL12 expression has been implicated in immune escape, metastasis and drug resistance in several tumor types, including GC." (PMID 41376630, 2025). "High levels of CXCL12 secretion by tumor-associated stromal cells is able, in a paracrine way, to enhance cell proliferation, induce epithelial-to-mesenchymal transition (EMT) and increase the migration and invasiveness at the tumor margin." (PMID 40307933, 2025). "Its sole ligand, CXCL12, is secreted by stromal cells (cancer-associated fibroblasts (CAFs), mesenchymal stem cells, and endothelial cells) in the tumour microenvironment (TME)." (PMID 41002447, 2025). "In contrast, a tumor stroma enriched with mesenchymal cytokines like C-X-C motif chemokine 12 (CXCL12) and insulin-like growth factor 1 (IGF1) predisposes primary cancer cell population to home into the bone marrow." (PMID 41223092, 2025). "We focused on CXCL12, a chemokine closely associated with tumor metastasis activity and angiogenesis." (PMID 40514659, 2025). "CXCL12 plays its role by recruiting Tie2 + macrophages, a population strongly associated with vasculature and tumor angiogenesis." (PMID 39003350, 2024). "Tumor-associated lymphatic endothelial cells upregulate CXCL12 expression, which then interacts with CXCR4 in T cells." (PMID 39107856, 2024). "CXCL12 can be released by injured hepatocytes, biliary epithelial cells, sinusoidal endothelial cells, tumor-associated leukocytes, and HCC cells themselves and have proinflammatory, profibrotic, and proangiogenic functions." (PMID 38767772, 2024). "CXCL12 appears to play a role in recruiting Tie2+ macrophages, which are closely associated with blood vessels and contribute to tumor angiogenesis." (PMID 39317708, 2024). "The results of this study also found that the mRNA and protein expression of CXCL12 was remarkably increased in the spinal cord of mice with pain caused by tumor cell implantation." (PMID 39641645, 2024). "With its conventional receptor, CXCR4, CXCL12 modifies immunity by immune cell recruitment and polarization, such as altering tumor-associated macrophages and T cells, eventually promoting malignancies." (PMID 38898023, 2024). "Increased secretion of CXCL12 has been associated with tumor chemorepellent activity towards antigen-specific T cells and with escape from immune control in melanoma and in pancreatic ductal adenocarcinoma (PDA) murine models." (PMID 39596815, 2024). "In this context, iCAFs are able to secrete chemokines, such as CXCL12, associated with chemotaxis and immune infiltration in the tumor microenvironment." (PMID 39003267, 2024). "Immunohistochemical analyses reveal that high levels of CXCL12/CXCR4 are associated with increased tumor aggressiveness and metastatic potential." (PMID 39682247, 2024).
tumor (continued). "One possible mechanism for this refractory disease lies in the coordinated interplay between tumor cells and cancer-associated fibroblasts (CAFs), including that through the C-X-C chemokine receptor type 4/C-X-C motif chemokine 12 (CXCR4/CXCL12) signaling." (PMID 38587644, 2024). "Considering that CXCL12 attracts infiltration of tumor-associated macrophages (TAMs), which are a significant source of VEGFA and vital chemoattractant for macrophages." (PMID 38611849, 2024). "The CXCR4/CXCL12 axis appears to be tumor-promoting; increased expression of CXCR4 was linked to more aggressive behavior and metastasis in various tumor types, including prostate cancer." (PMID 36982302, 2023). "Secretion of CXCL12 from fibroblasts has previously been linked with enhanced tumor growth, angiogenesis and recruitment of T-regulatory cells." (PMID 36635273, 2023). "Some results have shown that the expression of CXCL2 is associated with NF-κB activation involved in tumor invasion and metastasis, and the chemokine CXCL12 recruits immune cells infiltrating cancerous foci and triggers tumor-associated inflammation." (PMID 37994159, 2023). "It has also been reported that CXCL12 is secreted from cancer‐associated fibroblasts (CAFs) and that it plays an immunosuppressive role in the tumor microenvironment." (PMID 36300800, 2023). "On the other hand, CXCL12 is produced by several solid tumors and tumor-associated MCs express CXCR4." (PMID 37047288, 2023). "In primary cancer biopsies, we found a significant association between high density of CXCL12 + tumor-infiltrating immune cells and improved response to chemotherapy (p = 0.005)." (PMID 37966614, 2023). "CXCL12 is an important chemokine in T and NK cells that helps macrophages polarize into tumor-associated macrophages." (PMID 37575253, 2023). "A study of tumor-associated fibroblast (CAF)-induced monocyte migration revealed that CXCL12-supplemented media significantly increased monocyte chemotaxis." (PMID 37153567, 2023). "Another mechanism of AMD3100 antitumor activity was to block CXCR4+ tumor cells from interacting with CXCL12 produced by cancer associated fibroblasts." (PMID 37114134, 2023). "Recent study also showed that loss of lymphatic-specific CXCL12 boosts T cell retention and enhances tumor control." (PMID 37359565, 2023). "Another interesting observation in the present study is the association of the tumor CXCL12 expression with response to adjuvant chemotherapy." (PMID 37227446, 2023). "In the present study, we found that a high percentage of NSCLC tumor cells (85.3%) and cancer-associated fibroblasts (65.9%) express CXCL12." (PMID 37227446, 2023). "TM4SF1+, SOX4+, and MKI67+ tumor cells; CXCL12+ cancer-associated fibroblasts; CD4+ resident memory T cells; Treg; IgA+ plasma cells; and several myeloid subsets were enriched in stage IV CRC, most of which were associated with overall survival of patients." (PMID 37360193, 2023). "It was demonstrated that CXCL12 positively associated with tumor grade and stage in BlCa patient tissues, being CXCL12 expression more intense in recurrent patients." (PMID 36699696, 2022). "Several reports elucidated that tumor-associated lymphatic vessels, but not normal lymphatic vessels, express a high concentration of CXCL12, highlighting an active role for the tumor-associated lymphatic endothelium in metastatic tumor spread." (PMID 36679904, 2022). "In the current study, CXCL12 maintained a 0.29 fold-change in MCTVTs, while loss of CXCL12 promotes tumour migration to the liver, bone marrow, and lung." (PMID 34980125, 2022). "CXCL12/CXCR4 was reported to drive the accumulation of tumor-associated macrophages in the tumor environment or egress to draining lymphatics." (PMID 35615089, 2022). "In vitro and preclinical in vivo studies of this axis with rosiglitazone, known to inhibit the downstream signaling of CXCR4, caused the increased expression of CXCL12 in the tumor cells and decreased invasion." (PMID 36358665, 2022).
tumor (continued). "Cancer- or tumor-associated fibroblasts (CAFs/TAFs) also secrete tumor promoting CXC chemokine stromal cell-derived factor-1 (SDF-1)/CXCL12." (PMID 35486660, 2022). "Binding to CXCR4 turns these cells into carcinoma-associated fibroblasts (CAFs), which start to secrete CXCL12, which, in turn, acts on CSCs and tumor cells, further enhancing proliferation and/or the metastatic potential towards novel sites." (PMID 36293358, 2022). "Significantly, macrophage polarization has also been reported in prostate cancer, in which CAFs secrete numerous cytokines, such as IL-6 and CXCL12, and cause tumor-associated macrophages (TAMs) to transition into a tumor-promoting phenotype." (PMID 36244987, 2022). "CXCL12 promotes the recruitment of Tumor Associated Macrophages (TAMs), which usually adopt the M2 phenotype and favor tumor progression." (PMID 35565443, 2022). "In GC, it is reported that high expression of CXCL12/CXCR7 is markedly associated with advanced tumor stage, lymph node metastasis, and liver metastasis, and aberrantly activated CXCL12/CXCR7 promotes the malignant biological behaviors of GC cells." (PMID 35226830, 2022). "The expression of CXCR4 and CXCL12 mRNAs in glioblastoma increases with tumour grade and is associated with regions of necrosis and angiogenesis." (PMID 36140541, 2022). "The, CXCL12 expressed by cancer-associated fibroblasts binds to CXCR4 on tumor cells and induces EMT, which ultimately promotes metastasis." (PMID 35406450, 2022). "While CXCL12 is mainly secreted by cells associated with the tumor microenvironment, CXCR4 is expressed by ECs, cancer cells and cancer stem cells." (PMID 35155581, 2022). "Increased expression of the CXCL12 chemokine is associated with an increased adhesive capacity of tumor cells, promotion of angiogenesis, and faster development of metastasis." (PMID 36012171, 2022). "Both CCL2 and CXCL12 are found to be highly secreted in a broad range of cancers and are often associated with poor prognosis, underscoring them as targets for anti-tumor therapy." (PMID 36568151, 2022). "CXCL12 is associated with promotes CRC tumor cell growth, liver migration, survival rate and recurrence rate." (PMID 35114976, 2022). "CXCL12 is able to promote local invasion of neoplastic cells, while loss of CXCL12 expression in primary tumor site supports the migration of cancer cells to organs exhibiting high amount of CXCL12." (PMID 35203510, 2022). "CXCL12 is expressed at high levels in cancerous tissues; the main producer of CXCL12 is tumor-associated fibroblasts." (PMID 35893797, 2022). "CXCL12 notably contributes to the recruitment of Tumor-Associated Macrophages (TAM) in hypoxic regions, as evidenced in murine astrocytoma models." (PMID 36230504, 2022). "The results showed the upregulation of RANK-L, RANK, OPN, CXCR4, RUNX2 and FLT1 and the downregulation of OPG and CXCL12 genes, underlining their involvement and promising role in these neoplasms." (PMID 35203581, 2022). "The studies focusing on the role of macrophages have shown that tumor-associated macrophages (TAMs) play a dominant role in mediating CXCL12/CXCR4-induced liver metastasis of CRC." (PMID 36230645, 2022). "CXCL12 expression was observed mainly in tumor cells and, in some cases, in cancer-associated fibroblasts." (PMID 36359736, 2022). "Analysis of a publicly available data (TCGA PRAAD cohort) from a cohort of 422 PCa patients revealed that high CXCL12 expression is associated with a significantly higher rate of biochemical tumor recurrence." (PMID 35717322, 2022). "The formation of a dense ECM is closely related to the secretion of various factors (collagens I, III, IV, and V, as well as VEGFA, EGF, FGF, HGF, and CXCL12) by tumor-associated fibroblasts in tumor tissue." (PMID 35566065, 2022).
tumor (continued). "They discovered that CXCR4 inhibition with AMD3100 attenuated CXCL12 release from cancer-associated fibroblasts (CAFs), and concomitant treatment with an anti-PD-L1 antibody reactivated tumor immune recognition and eradicated PDAC in a murine model." (PMID 35797269, 2022). "CXCL12 (also known as SDF1) is an important cytokine in the PCa stromal compartment and associated with tumor aggressiveness." (PMID 35717322, 2022). "In invasive breast carcinomas, CXCL12-secreting carcinoma-associated fibroblasts (CAFs) directly influenced tumor growth." (PMID 34503058, 2021). "Tumor-associated fibroblasts (TAFs) mediated monocytes’ migration into tumor sites by secreting CXCL12 and induced their transformation into CD14+HLA-DR-/low MDSCs by IL-6 mediated STAT3 activation." (PMID 34680276, 2021). "This was attributed to the ability of cancer associated fibroblasts to trigger tumor angiogenesis through the recruitment of endothelial progenitor cells facilitated by CXCL12." (PMID 34445691, 2021). "Tumor-growth inhibition was associated with the increased expression of CXCL12 and the decreased expression of the two receptors in the human component of the tumor mass, along with a reduced vascularization of the tumor." (PMID 34834449, 2021). "Apart from tumor growth and angiogenesis, the CXCL12/CXCR4 axis is widely known for its role in predisposing the metastatic niche." (PMID 34503058, 2021). "The expression of CXCL12 and its receptors is associated with tumor invasion, angiogenesis, and lymph node metastasis in EC." (PMID 33390169, 2021). "A hypoxic tumor microenvironment favors up-regulation of CXCR4 and CXCL12 in monocytes, monocyte-derived macrophages, tumor-associated macrophages, endothelial cells, and cancer cells through a global regulator hypoxia-inducible factor-1 alpha (HIF-1α)." (PMID 34298991, 2021). "Senescent tumor cells inhibit CD8+ T cell infiltration by secreting a high concentration of CXCL12, which induces a loss of CXCR4 in T cells that result in impaired directional migration." (PMID 33643790, 2021). "Several other agents, such as CXCL12-based imaging agent and bioluminescence, have been developed for tumor diagnostic imaging." (PMID 33710803, 2021). "The CXCL12/CXCR4 ligand/receptor complex is associated with tumor progression, angiogenesis, metastasis, and survival in various malignancies." (PMID 34842843, 2021). "Constant CXCL12 production causes CXCR4a downregulation and desensitization, resulting in a resting state of tumor cells and antagonizing the metastatic process." (PMID 34830196, 2021). "For instance, FAP-positive CAFs suppress the anti-tumor efficacy by expressing CXCL12, which causes T-cells in tumors exclusion and regulates adaptive immunity." (PMID 34692696, 2021). "Cox regression univariate and multivariate analysis adjusted for Ki67 and Weiss score further suggested that high CXCL12 local expression is associated with less aggressive tumors and confers protection against tumor progression and recurrence." (PMID 34834449, 2021). "To gain insight into the possible role of the CXCL12/CXCR4/CXCR7 axis in tumor development and progression, we explored any association between the expression of the two receptors, or of their ligand, and the clinical characteristics of ACC patients." (PMID 34834449, 2021). "Accordingly, 10 nM CXCL12 also caused tumor cell phagocytosis in co‐cultures of MM cells and macrophages." (PMID 33956406, 2021). "Different microglial-derived factors including proteases (e.g., Ctss, Mmp3, and Mmp9), Wnt signaling components or chemokines (e.g., Cxcl12) have been implicated in assisting tumor cells to cross the BBB and colonize the brain parenchyma." (PMID 33384994, 2020). "In line with this, it has been demonstrated that co-implantation of tumor cells with fibroblasts expressing CXCL12 enhances tumor growth and CXCL12 overexpression has been linked to increased metastasis and poor prognosis." (PMID 33114046, 2020).
tumor (continued). "In CLL, Ibrutinib causes redistribution of tumor cells from lymph nodes (LN) into the peripheral blood (PB) and inhibits their migration towards CXCL12 gradients." (PMID 32370190, 2020). "Compelling evidence has demonstrated that CXCL12/CXCR4/CXCR7 axis is implicated in tumor growth, survival, angiogenesis, metastasis, tumor microenvironment, and chemoresistance." (PMID 33363463, 2020). "In contrast, CXCL12 is associated with tumor initiation and progression and is involved in the recruitment of plasmacytoid dendritic cells (pDCs)." (PMID 33396862, 2020). "CXCL12 has been shown to be associated with tumor angiogenesis and tumor cell hypoxia tolerance in an in vivo glioma model." (PMID 33511267, 2020). "Tumor metastasis is usually associated with abnormal expression of cytokines, especially CXCL12, VEGF, IL1β, and IL6, while CAFs can promote tumor growth and invasion via a plethora of active factors." (PMID 31636361, 2020). "This in turn would lead to a predisposition of disseminated tumor cells to colonize the bone marrow which has a higher abundance of stromal -derived CXCL12 and IGF-1 compared to other metastatic sites such as lung, liver and brain." (PMID 32232008, 2020). "In a preclinical mouse model, targeting of chemokine ligand 12 (CXCL12) improved antitumor immunity and caused tumor reduction via T cell activity and upregulation of PD-L1 and CTLA-4, highlighting the role of CXCL12 in immune response evasion." (PMID 33050151, 2020). "Serum CXCL12 levels were associated with nodal involvement while CXCL5 concentrations were associated with depth of tumor invasion and distant metastasis." (PMID 33182840, 2020). "It has been reported that CXCL12/CXCR4 axis plays an important role in tumor angiogenesis, and protein and mRNA levels of CXCL12 are associated with human BCa progression." (PMID 32675942, 2020). "The infiltration of MDSCs from the periphery to the hypoxic area of the tumor is associated with the hypoxia-dependent increase in the expression of stromal-derived factor 1 (SDF1, CXCL12)." (PMID 31540045, 2019). "In another example, our data suggests that tumour type susceptibility to anti-CXCR4 ADCs is also determined by tumour anatomical location and associated CXCL12 levels." (PMID 30792442, 2019). "A transcriptional study on recurrent AC disclosed the upregulation of 16 genes and a significant association of tumor relapse with the expression of CXCL12 and CXCR4." (PMID 31191748, 2019). "Cytokines and chemokines derived from tumor cells and cancer-associated fibroblasts (CAFs), such as CSF-1, CXCL12/SDF1, CCL2/MCP-1, CCL5/RANTES, and VEGF, recruit mononuclear cells into the tumor microenvironment and activate them to become TAMs or MDSCs." (PMID 31554173, 2019). "FAPα-positive cells in the primary tumor microenvironment have been associated with immune suppression, promoting T cell exclusion via secretion of CXCL12." (PMID 31058816, 2019). "Overexpression of CXCR4 has been implicated in tumour metastasis and has been found to metastasise to tissues with a high concentration of CXCL12, such as lungs, liver and bone marrow." (PMID 29959873, 2018). "A recent preclinical study by Li and colleagues demonstrated radiation (1 × 4 Gy) to enhance the tumor-promoting effects of CAFs, an effect that was associated with increased expression of CXCL12." (PMID 30105016, 2018). "It has investigated that genetic polymorphisms of CXCL12 involving various environmental factors in the growth and development of tumor pathogenesis." (PMID 28929029, 2017). "In BC, the expression analysis of CXCL12 gene and its association with tumor stages has been evaluated in different inhabitants all over the world." (PMID 28929029, 2017). "It is difficult to fathom how CXCL12 gradients can cause cancer cell migration into blood vessels because of the presence of endothelial CXCR7 on most tumor vasculature." (PMID 29117251, 2017).